ERBB2 (erb-b2 receptor tyrosine kinase 2)
Diseases named in the same sentence as ERBB2 in open-access papers (continued):
Sharing a sentence is not in itself a finding about the gene and the disease.
breast cancer (continued). "Moreover, when assessing breast cancer subgroups, PIK3R1 was predominantly underexpressed in HR-/ERBB2- and HR-/ERBB2+ tumors (p < 0.0000001), while PIK3CA was deregulated in only a minority of tumor samples: overexpressed in 18 (3.9%) and underexpressed in 40 (8.7%) cases." (PMID 24229379, 2013). "Expression of an activated ErbB2 mutant or over-expression of wildtype ErbB2 (as in Her2 breast cancers), together with decreased PTPN13 expression or function, not only enhances complex formation but also leads to EphrinB1 phosphorylation and associated downstream signaling." (PMID 22279592, 2012). "This is further exemplified in breast cancer mouse models: while overexpression of AKT1 accelerates ErbB-2 mediated mammary tumorigenesis and suppresses tumor invasion, overexpression of AKT2 markedly increases the incidence of pulmonary metastases in breast cancer." (PMID 22666248, 2012). "Triple negative breast cancer (TNBC) is an aggressive and heterogeneous subtype of breast cancer defined by the absence of estrogen (ER) and progesterone (PR) steroid hormone receptor expression and lacking high expression and/or amplification of HER2/ERBB2." (PMID 22812567, 2012). "The two patients with metastatic breast cancer who had experienced an objective response to breast cancer-specific modulation frequencies had tumours that over-expressed oestrogen receptor (ER+) and progesterone receptor (PR+), but did not over-express ERBB2 (ERBB2−)." (PMID 22134506, 2012). "With respect to breast cancer, ErbB2/EphrinB1 signaling may be most relevant in tumors with high ErbB2 expression and either low/absent PTPN13 expression or those harboring PTPN13 functional mutations." (PMID 22279592, 2012). "More importantly, we have previously demonstrated a functional coupling of S1P4 with HER2, suggesting that combined treatment of cells with S1P4 antagonists and ErbB2 inhibitors might represent a more effective treatment regime for ER− breast cancer patients compared with ErbB2 inhibitors alone." (PMID 22460268, 2012). "Not all breast cancers that overexpress ERBB2 respond to Trastuzumab." (PMID 21364580, 2011). "Interestingly, in breast cancers, TRAF4 amplification can occur independently of ErbB2 amplification suggesting that TRAF4 may be the target of a more centromeric amplicon than the one involving ErbB2." (PMID 24212830, 2011). "Given the reduced expression of IGFBP3 in the C3.6 cells, IGFBP3's reported role in regulating IGF activity and the reported aberrant regulation of the IGF system in breast cancer, we wanted to further examine if IGF1-induced signalling might be affected by ErbB2 overexpression in these cells." (PMID 20840765, 2010). "Without subsidies, many Asian patients with ErbB2-positive breast cancer may not be able to afford ErbB2-targeted treatments, which in turn, may reduce the incentive for ErbB2 assessment." (PMID 20715159, 2010). "Thus, the «group query» genes ERBB2, ESR1, CEACAM5 and AR are well known markers of breast cancer." (PMID 20158879, 2010). "Previous studies have demonstrated that the negative effect on the prognosis of breast cancer attributed to ERBB2 amplification could, in fact, be due to co-amplification of the region adjacent to ERBB2." (PMID 20158880, 2010). "The amplification of ERBB2/HER2 is usually detected in no more than 20% of breast cancer patient." (PMID 20070913, 2010). "C17ORF37 protein expression is linked with ERBB2-amplification in most cases, however, it has also been observed in breast carcinomas that do not overexpress ERBB2, and particularly in early stage and infiltrating lobular carcinomas that typically do not overexpress ERBB2." (PMID 20932292, 2010). "ErbB2 is also overexpressed in some ERα-negative breast cancers and prostate cancers." (PMID 19383165, 2009). "Second, it is not clear whether the mammary tumours arising in this WAPcre;Brca1F11/F11;Trp53F5–6/F5–6 mouse model do or do not express ER, PR and ERBB2." (PMID 19904273, 2009).
breast cancer (continued). "A similar reasoning may explain our observation of a trend to worse 10-year survival among ERBB2-amplified node-negative gastric carcinomas, something that was also reported by others in breast carcinomas." (PMID 19156142, 2009). "The ErbB family (ErbB1/EGFR, ErbB2/HER2, ErbB3/HER3 and ErbB4/HER4) of receptor tyrosine kinases (RTKs) is known to drive both formation and progression of a number of commonly occurring cancers, including breast cancer, due to the normal role of these RTKs in regulating cell growth and survival." (PMID 18841159, 2008). "Since trastuzumab targets the extracellular domain of HER2 (ErbB2) and lapatinib acts intracellularly with specificity for both the ErbB1 and ErbB2 receptors, this combination may prove to be of value in patients with HER2 (+) breast cancer." (PMID 21611006, 2008). "On the other hand, not all breast carcinomas overexpressing ERBB2 respond to trastuzumab." (PMID 18454161, 2008). "A panel of 20 different breast cancer samples was chosen to represent these three common phenotypes (9/20, ErbB2-positive/ER-negative; 4/20, ErbB2-positive/ER-positive; 7/20, ErbB2-negative/ER-positive) and was blindly analyzed for miRNA expression levels by microarray profiling." (PMID 16784538, 2006). "Furthermore, blocking ER using antisense strategies resulted in increased ErbB1, no change in ErbB2 and a slight decrease in ErbB3 expression in breast cancer cells." (PMID 16519802, 2006). "For example, the tyrosine kinase receptor ErbB2, amplified in 30% of breast cancers, is important for early steps in terminal end bud formation and ductal extension into the mammary fat pad of mice, and MCF-10A cells expressing activated ErbB2 form multi-lobed, filled acinar structures." (PMID 16584539, 2006). "All of the tagSNPs in the CHEK2 and ERBB2 genes and two of the tagSNPs in the ATM gene were not only genotyped in breast cancer cases and controls who participated through blood sample donation, but were also genotyped in breast cancer cases who participated through tissue sample donation." (PMID 17132159, 2006). "ErbB2-positive and ER-positive breast cancers have been shown to exhibit significantly different gene expression profiles, however, gene expression studies to date have failed to discriminate ErbB2-positive/ER-positive breast cancers from either ErbB2-positive or ER-positive subgroups." (PMID 16784538, 2006). "We noted enhanced phosphorylated Akt and MAPK in a perivascular distribution in mammary tumors, with overexpression of both erbB2 and erbB3, suggesting that circulating HRG may enhance the physical and functional erbB2/erbB3 interactions in vivo, similar to what we observe in vitro." (PMID 16168116, 2005). "However, the association of ERBB2 expression with the expression of MMP-2 and MMP-9 has not previously been reported in breast cancer." (PMID 15054465, 2004). "AP-2α levels were not correlated with ERBB2 expression in non-breast cancer cell lines." (PMID 12942124, 2003). "Therefore, the sample may not represent all patients with early-stage HR-positive, ERBB2-negative breast cancer in the US, limiting the generalizability of the findings." (PMID 41632146, 2025). "Furthermore, while a strong relationship between ERBB2 (HER2) amplification and overexpression is well known for breast cancer, these tests may not be interchangeable for other tyrosine kinases or other cancer types." (PMID 38966170, 2024).
breast cancer (continued). "Additionally, recent advancements in adjuvant ET, particularly with the development of oral selective estrogen receptor degraders (SERDs), as investigated in the EMBER-433 and CAMBRIA-134 trials, offer promising alternatives for patients with ER-positive, ERBB2-negative breast cancer." (PMID 39509133, 2024). "This randomized clinical trial assesses whether neoadjuvant fulvestrant or anastrozole plus fulvestrant vs anastrozole alone increases endocrine-sensitive disease rate (ESDR) in postmenopausal women with estrogen receptor (ER)–rich/ERBB2-negative breast cancer." (PMID 38236590, 2024). "Moreover, there was crossover with pathways associated with several types of cancer, including glioma, renal cell carcinoma, and non-small-cell lung cancer, showing that the ERBB2 pathway plays an important role in multiple cancer types, not just breast cancer." (PMID 39684551, 2024). "BC is divided into three main subtypes based on specific biomarkers: hormone-receptor-positive/ERBB2-negative, ERBB2-positive, and Triple Negative Breast Cancer (TNBC)." (PMID 37513179, 2023). "Notably, a slightly higher percentage of patients with a high AL presented with HR negative/ERBB2 negative breast cancer (345 patients [15.7%] vs 301 patients [13.3%]) or HR positive/ERBB2 negative cancer (420 patients [19.1%] vs 398 patients [17.6%]) than patients with low AL." (PMID 37200034, 2023). "Interestingly, in a conditional knockout mouse model, HK2 mediated KRas-driven lung carcinoma and ErbB2-driven generation and maintenance of breast cancer, and HK2 downregulation inhibited lung cancer in vitro and in vivo as well as the malignant biological behavior of breast cancer." (PMID 37854321, 2023). "Indeed, we showed that the ONCE protocol might be an informative approach to monitor ERBB2 in breast cancer patients without genomic ERBB2 amplification or patients that are HER2 positive at diagnosis and turn negative after multiple cycles of therapy." (PMID 38046436, 2023). "Breast cancer subtypes are classified as luminal A (Estrogen Receptor Alpha (ERα) positive, Progesterone Receptor (PR) positive, Erb-B2 receptor tyrosine kinase 2 (HER2) negative), luminal B (ERα+/PR+/HER2+), HER2+, or basal (ERα-/PR-/HER2-; triple negative BCa)." (PMID 35626710, 2022). "However, our study aimed to determine the association of AHT timing with the survival of patients with HR-positive, ERBB2-negative breast cancer who received AHT but did not receive chemotherapy, and was intended to examine the optimal initiation timing of AHT within the recommended 12 months." (PMID 35166783, 2022). "The objective of this qualitative study was to understand these subspecialists’ perspectives on SLNB omission and to identify specific practice factors that may be involved in deimplementation of SLNB in women 70 years and older with cT1N0 HR-positive, ERBB2-negative breast cancer." (PMID 36001314, 2022). "In the overall patient population, 1215 (31.0%) had HR-positive/ERBB2-negative cancer, 310 (7.9%) had ERBB2-positive/HR-positive cancer, 200 (5.1%) had ERBB2-positive/HR-negative cancer, 258 (6.6%) had TNBC, and the remaining 1933 patients (49.4%) had an unknown breast cancer subtype." (PMID 35960523, 2022). "In general, breast cancer can be broken down into three major categories based on the combination of receptor expression: hormone receptor (ER or PR) positive/ERBB2 negative (HR+/ERBB2–), ERBB2 positive/hormone receptor positive or negative (ERBB2+/HR– or HR+), and triple-negative (HR–/ERBB2–)." (PMID 33670942, 2021). "The difference in findings may also have occurred for other reasons, such as differences in patient populations (eg, the inclusion of only patients with lymph node–negative, ER-positive/ERBB2-negative breast cancer in the present analysis) or differences by treatment." (PMID 34190995, 2021).
breast cancer (continued). "Furthermore, we analyzed 35 autophagy genes involved in the classical autophagy pathway and found that ATG12 and MAP1LC3B are the only genes which upregulation is correlated with worse RFS-based survival probability in patients with ERBB2-positive but not ERBB2-negative breast cancer." (PMID 33801244, 2021). "Moreover, DEPTOR is located on the cell membrane in ErbB2-positive breast cancer tissues, but not in tumor-adjacent normal tissues, indicating that DEPTOR may contribute to the oncogenic characteristics of ErbB2." (PMID 33995662, 2021). "Testing whether the circulating tumor cells display higher phospho-Erk levels than those composing respective primary ErbB2-negative tumors would represent a promising direction of the studies aimed at verifying the role of Mek/Erk activity in ErbB2 expression in breast cancer patients." (PMID 29285258, 2017). "Considering that IGF1R deregulation is not limited to ErbB2+ breast cancer, our data widen the scope of breast cancer subtypes that may respond to phenformin treatment to include ErbB2-negative breast cancer with IGF1R deregulation, yet further investigation is necessary." (PMID 28947975, 2017). "Though a population of the HER2/ERBB2 subtype may harbor innate resistance to HER2 inhibitors, or a subset of other subtypes may show response, the large enrichment within the HER2/ERBB2 subtype suggests the accurate prediction of responders to HER2 inhibition within breast cancer patients." (PMID 28649435, 2017). "Furthermore, unlike breast cancer, heterogeneous ErbB2 immunostaining has been reported in CRC." (PMID 25416285, 2014). "Additionally, the recurrent occurrence of low erbB-2 expression levels in cat mammary tumours suggests that cat mammary neoplasias could be a valuable model for erbB-2 negative human breast cancer." (PMID 24386251, 2013). "Finally, using a transgenic mouse model that co-expressed ErbB2 and Cre recombinase, we demonstrated that while mammary epithelial ablation of FAK delayed tumour onset and reduced the number of neoplastic lesions, animals developed mammary tumours with 100% penetrance." (PMID 22373082, 2012). "Importantly, none of the mouse mammary tumors showed the tandem duplication phenotype that we have observed in human BRCA1-mutated and triple-negative breast tumors (that is, tumors that do not express ERBB2, and estrogen and progesterone receptors)." (PMID 20942901, 2010). "Similarly, in 38 breast cancer cell lines, the expression of the ERBB2 gene was significantly correlated with the expression of all the 5 members of the TNFAIP1/POLDIP2 SFGM, although the total number of observed significant correlations was less than for the breast cancer patients." (PMID 20158880, 2010). "HER2-low breast cancer, also known as IHC 1+ or IHC 2+ without ERBB2 amplification, is a new concept in the biology of breast cancer that has removed the binary classification of HER2-positive or HER2-negative breast cancer." (PMID 42075798, 2026). "Triple-negative breast cancer (TNBC) is a clinical subgroup of breast cancer defined by negativity for the estrogen receptor (ER), progesterone receptor, and ERBB2/HER2 gene amplification." (PMID 41212151, 2025). "In HER2-positive breast cancer, ERBB2 gene amplification leads to HER2 overexpression, and patients without anti-HER2 treatment have more aggressive tumors and poorer patient prognosis." (PMID 40552265, 2025). "Recently, a subset of breast cancers with low HER2 expression and no apparent ERBB2 amplification has been approved for novel anti-HER2 medicines, particularly HER2-targeting ADCs." (PMID 39211554, 2024).
breast cancer (continued). "The hormonal-related genes studied (ESR1, CYP19A1, and PGR) were not expressed by MCF10-DCIS cancer cells that are HER2-enriched (ER−, PR−, HER2+/ERBB2+) intrinsic molecular subtypes of breast cancer." (PMID 39072314, 2024). "NT2.5-LM lung metastases are ERBB2-positive, express similarly low levels of AE1/3 and EGFR, and are similarly negative for CK5 and CK6, when compared to NT2.5 mammary tumors." (PMID 38717519, 2024). "In contrast, only NKAB-EGFR displayed binding to MDA-MB468 breast carcinoma cells, which highly overexpress EGFR but are negative for ErbB2." (PMID 38334638, 2024). "Breast cancer with the genetic signature of ER-negative, PR-negative, and ERBB2/HER2-negative has been classified as triple-negative breast cancer (TNBC), which represents the most aggressive clinical subtype with a poor prognosis." (PMID 37813891, 2023). "Xpert Breast Cancer STRAT4 is a RT-qPCR platform that studies the mRNA expression of ESR1, PGR, MKI67 and ERBB2, providing a positive or negative result for each of these breast cancer biomarkers." (PMID 36980575, 2023). "In breast cancer, ERBB2 amplification is a well‐known prognostic biomarker of poor survival in the absence of anti‐HER2 therapy." (PMID 36670542, 2023). "ERBB2/HER2 is a marker that is not expressed in TNBC, and HER2+ breast cancers respond well to trastuzumab (anti-HER2)." (PMID 36672349, 2023). "Is high body mass index (BMI) a factor associated with a high 21-gene recurrence score in estrogen receptor (ER)–positive, ERBB2-negative (formerly HER2 or HER2/neu) breast cancer, especially in younger patients (≤45 years) with breast cancer?" (PMID 36441548, 2022). "Triple-negative breast cancer (TNBC) is a subtype of breast cancer characterized by the absence of estrogen receptor, progesterone receptor, and HER2/ERBB2 expression and known for being aggressive and having a poor prognosis." (PMID 36096830, 2022). "About 15%–20% of breast cancers involve the HER2 + receptor, now known as ERBB2 +, and about 15% of breast cancers are triple-negative and do not have ER, PR, or ERBB2 protein in the cancer cells." (PMID 36091438, 2022). "The ERBB2-negative MDA-MB-468 breast cancer cell line was used as a negative control (MDA-MB-468, MFI 1.2 ± 0.2, n = 3), while the MDA-MB-453 breast cancer cell line served as a positive control (MDA-MB-453, MFI 138.1 ± 26.3, n = 3)." (PMID 33809981, 2021). "This subset had reduced expression for genes involved in immune response and reduced accessibility at regions proximal to metabolism genes, despite no measurable difference in expression for typical breast cancer markers, such as PR, ESR1, and ERBB2." (PMID 34922480, 2021). "All 19 non-breast tumors showed ERBB2 amplification (estimated CN above 3.0) but their HER2 IHC score varied, indicating that NGS-derived CN amplification and IHC scoring systems are not as concordant in non-breast cancers as in breast cancers." (PMID 33710417, 2021). "ErbB receptors, especially ErbB2 and EGFR, are overexpressed in many cancers such as non-small-cell lung cancer, ovarian cancer, and breast cancer." (PMID 33763152, 2021). "We also noticed that trastuzumab upregulates ITB1, GNAS2, and GNA13 in EVs emitted by trastuzumab-sensitive breast cancer cells MCF7/Her2-18, but not in EVs emitted by ErbB2-positive trastuzumab-resistant human breast cancer cells HCC-1419." (PMID 33023655, 2020). "We found that high WT1 mRNA expression was associated with high histological grade, estrogen receptor (ER)-negative status, basal-like subtype, and ERBB2 (erb-b2 receptor tyrosine kinase 2, HER2) subtype in breast cancer patients." (PMID 32210734, 2020). "Triple negative breast cancer (TNBC) refers to breast cancer that lacking estrogen receptors (ER), progesterone receptors (PR), and HER2 (ERBB2) expression." (PMID 30988073, 2019).